IFIT1 (interferon induced protein with tetratricopeptide repeats 1)
Description:
Plays a key role in the innate immune response as part of an interferon-dependent multiprotein complex, recognizing and sequestering viral RNAs that lack host-specific 2'-O-methylation at their 5' cap. By distinguishing these RNAs from host mRNAs, inhibits their translation by competing with the translation initiation factor eIF4E. Could also prevent viral replication through its interaction with DNA replication origin-binding protein E1 of several viruses. Causes the translocation of E1 from the nucleus to the cytoplasm and can also inhibit its helicase activity in vitro. Exhibits antiviral activity against many viruses from the Flaviviridae (West Nile virus, Dengue virus, hepatitis C virus), Coronaviridae (human 229E coronavirus, SARS-CoV-2 and SARS-CoV), Poxviridae (vaccinia virus) and Togaviridae (Sindbis virus) families.
Synonyms: IFIT-1; IFI-56K; P56; G10P1; IFI56; IFNAI1; ISG56; GARG-16; C56; IFI-56; RNM561
Tractability: PROTAC: UniProt records ubiquitination sites on it; ubiquitination databases record sites on it; its protein half-life has been measured.
Gene: Protein-coding gene on chromosome 10 (89,392,546 to 89,406,487, forward strand). Ensembl gene ENSG00000185745.
Subcellular location: Cytoplasm
Subcellular location (Human Protein Atlas): Cytosol
Pathways (Reactome):
Immune System: ISG15 antiviral mechanism; Interferon alpha/beta signaling
Gene Ontology:
Molecular function: enzyme inhibitor activity; protein binding; RNA binding; RNA sequestering activity
Biological process: antiviral innate immune response; cellular response to exogenous dsRNA; cellular response to type I interferon; intracellular transport of viral protein in host cell; negative regulation of viral genome replication; negative regulation of viral translation; positive regulation of viral genome replication; response to virus; cellular response to cytokine stimulus; response to other organism
Cellular component: cytoplasm; cytosol; host cell
Genetic constraint (gnomAD): Loss-of-function variants: 0 observed, 1.44 expected, observed/expected ratio (o/e) 0, 90% interval 0 to 1.58. That is too few expected variants to judge how well the gene tolerates losing a copy. Missense variants: 489 observed, 571.81 expected, observed/expected ratio (o/e) 0.86, 90% interval 0.79 to 0.92. Synonymous variants: 185 observed, 208.44 expected, observed/expected ratio (o/e) 0.89, 90% interval 0.79 to 1.
Homologues: Orthologues: chimpanzee IFIT1 (98% identical), macaque IFIT1 (91% identical), pig IFIT1 (66% identical), tropical clawed frog ifit5l (40% identical), tropical clawed frog ifit5 (36% identical), tropical clawed frog ifit1b (35% identical), zebrafish ifit10 (33% identical), zebrafish ifit11 (32% identical), zebrafish ifit12 (31% identical), zebrafish ifit8 (26% identical), zebrafish ifit14 (22% identical), zebrafish ifit15 (22% identical), and 1 more. Paralogues in human: IFIT1B (67% identical), IFIT5 (56% identical), IFIT2 (44% identical), IFIT3 (42% identical).
Diseases named in the same sentence as IFIT1 in open-access papers:
IFIT1 is named in the same sentence as 135 diseases in open-access papers, as found by Europe PMC text mining. Sharing a sentence is not in itself a finding about the gene and the disease. The quoted sentences say what the papers report.
viral infection (161 papers, 2006 to 2026). "Among these genes, DDX58 and IFIT1 are highly associated with cytokine response, the NF-kappa B signaling pathway, and immune responses to virus infection." (PMID 33301474, 2020). "An increased expression of IFIT1 was found in established RA patients, suggesting its potential association of viral infections with autoimmune diseases." (PMID 31024609, 2019). "In line with this, in H1N1/WSN and H5N3 virus infection an elevated level of IFIT1 was associated with increased expression of anti-apoptotic genes XIAP associated factor 1 (XAF1) in both viruses and TNF receptor-associated factor 1 (TRAF1) in H5N3 virus infection in response to early cell death." (PMID 28558796, 2017). "IFIT1 expression in neutrophils enhances their antimicrobial capacity, particularly against viral infections." (PMID 40626180, 2025). "The results revealed that significantly lower IFIT1 and MxA expressions were detected compared to the WT virus infection." (PMID 39972477, 2025). "The activation of the interferon response was further validated by the upregulation of MX1 and IFIT1, both have shown in prior virology studies to restrict viral replication, thereby reinforcing the relevance of the model to house viral infections." (PMID 41050093, 2025). "Children with unexplained fever and low CRP had differentially expressed genes linked to interferon-induced immune responses, including IFIT1, IFIT2, and IFIT3, commonly upregulated during viral infections." (PMID 40806258, 2025). "The IFIT1 gene, located at 10q23, is induced by type 1 interferons or viral infections and exhibits extensive antiviral activities as well as anti-inflammatory effects." (PMID 40510586, 2025). "Overlapping genes between the two viral infections surge to 426, with IFIT1 and CXCL10 highly ranked, suggesting a state of sustained immune activation and highlighting the complexity of host responses as the infection progresses." (PMID 39591472, 2024). "The induction of OAS1, OAS2, and OASL, which, as main sensors for viral infections, explains the induction of numerous interferon-induced proteins (e.g., IFIT1, IFIT2, IFI44, MX1, MX2)." (PMID 39062793, 2024). "Another interesting gene found to be upregulated in ET rats as compared to PF rats is IFIT1, a conserved antiviral gene activated upon interferon signaling and commonly found to be upregulated in response to viral infection." (PMID 38271377, 2024). "The ISG56/IFIT1 protein is an important protein in antiviral innate immune response because it prevents the spread of viral infection by inhibiting translation and replication." (PMID 38923445, 2024). "IFIT1 and IFNB1 expression was induced by viral infection, and we found that the fraction of cells expressing IFIT1 was higher than the fraction expressing IFNB1 at multiple timepoints in infection." (PMID 37814072, 2023). "We also found that IFIT1 mRNA is present at approximately 5.6-fold higher levels in the C7/10-derived virus infection than in the BHK-derived virus-infected cells." (PMID 37632027, 2023). "We found that the mosquito-derived virus has less IFIT1 protein expressed at 12 hpi, with there being approximately 3.2 times as much IFIT1 protein in the BHK-derived virus infection compared to the C7/10-derived virus infection." (PMID 37632027, 2023). "IFIT1 is induced by type I interferon stimulation in the present of double‐stranded RNAs or viral infection." (PMID 37817224, 2023). "The interferon-induced protein with tetratricopeptide repeats 1 (IFIT1), for example, is being induced at a 2.8 log2-fold change increase in the mosquito-derived virus infection compared to the mammalian-derived virus infection." (PMID 37632027, 2023). "IFIT1 transcription is strongly induced during virus infection and induction of IFIT1 expression can be detected well before IFNB1 expression." (PMID 37814072, 2023).
viral infection (continued). "Characterized over a decade later than eIF4E(K119A), Interferon-Induced protein with Tetratricopeptide repeats 1 (IFIT1) is a cap-dependent RNA-binding protein produced in cells in response to a viral infection as part of the vertebrate innate immune response." (PMID 36259646, 2022). "ISGs such as IFITs have been reported to be important for controlling virus infection in the brain, and we did find increased expression of Ifit1 and Ifit2 mRNA in the brains of INKV-inoculated B6 mice, despite the lack of significant IFN induction." (PMID 35245345, 2022). "We then quantified mRNA expression of IFN-β (type I IFN), IFN-λ (type III IFN), select ISGs (OAS2, IFIT1, IFIH1), and the neutrophil attracting chemokine IL-8 (CXCL8), which has been implicated in nasal inflammation during viral infection." (PMID 33811184, 2021). "The next gene, interferon-induced protein with tetratricopeptide repeats 1 (IFIT1), was upregulated 27.75-fold and encodes a protein that is important for innate immunity defense, specifically viral infection." (PMID 34573352, 2021). "Prior transfection of miR-24 inhibited IRF3 activation in HSV1 infected cells, whereas antimiR-24 enhanced it; consequently, IFN-β mRNA and IFIT-1 mRNA induction by virus infection was suppressed by miR-24 and augmented by antimiR-24." (PMID 34591940, 2021). "IFIT1 plays a crucial role in some viral infections, where hepatitis E virus polymerase binds to IFIT1 to shield the viral RNA from translation inhibition mediated by IFIT1 and enhances the interferon response in murine macrophage-like cells." (PMID 33301474, 2020). "Uncapped 5′-PPP viral RNA recognition by IFIT1 leads to the assembly of an IFIT1/2/3 complex that either sequesters RNA away from an actively replicating RNA pool or promotes RNA degradation, thus inhibiting viral infection." (PMID 32485916, 2020). "Despite the higher accumulation of viral proteins, expression of IFIT1 in response to virus infection was similar for both genotypes." (PMID 31856218, 2019). "This deubiquitinating enzyme has been shown to mediate the IFN-type I response upon viral infection and it has been associated with higher IFN-β and IFIT1 gene expression." (PMID 31467281, 2019). "Other members of the network also reappeared in the gene set enrichment analysis as members of pathways associated with viral infections (DDX58, IFIT1, IRF1, MX1, STAT1) or viral carcinogenesis and cell cycle (CCND1, CCND3, CCNE1, CDC20, E2F2, RANBP1)." (PMID 30042828, 2018). "IFIT inhibits viral infections through multiple mechanisms; IFIT1 and IFIT2 suppress the translation initiation, IFIT1 binds uncapped or incompletely capped viral RNA and sequesters viral protein (e.g., HPV E1) or RNA in the cytoplasm." (PMID 26052325, 2015). "The study found that IFIT1 bound 2′-O-unmethlyated RNA, which resulted in an inhibition of translation, and therefore decreased virus infection." (PMID 24653722, 2014). "The ability of IFIT1 to target viral RNAs selectively allows the cell to specifically fight virus infections while pursuing an antiviral program aimed at destroying the intruding pathogen." (PMID 24098121, 2013). "We found 12 downregulated genes involved in immune response and the immune response to virus infection, and interestingly, they were mainly related to the interferon family of anti-viral factors, such as IFIT1, IFIT3, and OASL." (PMID 22455445, 2012). "Among the IFN induced genes, IFIT1 and IFIT2 (also named ISG-54 and ISG-56), are known to be highly responsive to viral infection in CNS." (PMID 20927331, 2010). "Overall, the observed increase in MX2 and IFIT1 expression with BYBG may improve the trained innate immune response to future viral infection." (PMID 39846553, 2025). "While not as well studied as MX1, IFIT1 encodes for a family of IFN-induced proteins with tetratricopeptide repeats that are induced after viral infection or PAMP recognition." (PMID 38932231, 2024).
viral infection (continued). "A greater number of genes are upregulated in DCs after MRV infection, many of which are involved in the innate immune response (i.e. Ifit1, Ifit3, Mx1, Gbp2, Oasl1, Isg15, Ccr1, Ifitm2, Oaxl2, Casp1, Casp4) that would be predicted in response to a viral infection." (PMID 38895117, 2024). "VSV-induced Ifn-β and Ifit1 expression was still largely lower in Irf3_P10A BMDCs than in WT BMDCs, indicating that HIF1α does not mediate the difference between WT and Irf3_P10A mice in response to viral infection." (PMID 38670937, 2024). "Under-expression of MX1, ISG15, RSAD2, IFIT1, and OAS2 may weaken the ability of the immune system to effectively counter viral infections, leaving the heart tissues susceptible to viral invasion and potentially contributing to MMVD progression." (PMID 38753730, 2024). "Tongue sole (Cynoglossus semilaevis) IFIT1 could be significantly induced by viral infection, which was proved to play a crucial role in antiviral defense by overexpression and knockdown assays." (PMID 37627029, 2023). "IFIT1 is a well-known regulator of viral infection-induced immune response and inflammation." (PMID 35034537, 2022). "The function and pathway enrichment analyses of M. tuberculosis H37Rv-infected macrophage by RNA-seq demonstrated that gene enrichment was closely associated with viral infection genes, including TRIM22, IFIT1, IFI44L, and IFI44, consistent with M. tuberculosis being an intracellular pathogen." (PMID 34722780, 2021). "During a viral infection, IFIT1 is an essential positive regulator of type I interferon production." (PMID 32499867, 2020). "However, the exact mechanistic role of nuclear localization of IFIT1 in LC and its effects on virus infection require further investigation." (PMID 31311882, 2019). "Moreover, the study of molecular effects of HPV transfection of trophoblast cells identified two candidate genes, ISG15 and IFIT1, possibly involved in the antiviral response after interferon induction upon viral infection." (PMID 28869524, 2017). "In addition, dozens ISGs, among which some have been characterized for their antiviral activities against various other viral infections, for example Mx1, Ifit1, Isg15, Ifi44, Ddx60, Oasl and Irf7 were up-regulated upon HDV inoculation in hNTCP-Tg mice." (PMID 25902143, 2015). "IFIT1 is commonly associated with IRF3 signaling in response to IFN treatment and viral infection." (PMID 21999375, 2011). "Finally, the overexpression of MX1, a well-characterized biomarker of viral infection; IFIT1, one of the top upregulated genes; and OAS1, OAS2 and OAS3, genes with a molecular function, 2-5-oligoadenylate synthase activity, identified as enriched in the DGE analyses, was confirmed by RT-qPCR." (PMID 42194954, 2026). "However, genes such as Ifitm10, Ifi203, Ifi205, Ifit1 and Ifit2 showed an upregulated transcription at 6 and 24 h, suggesting that expression of some antiviral genes is regulated by alternative pathways to ensure host-cell survival during viral infections." (PMID 39296294, 2024). "Thus, we speculate that the high basal levels of IFIT1 in the nuclei of LC may prime these cells to fight virus infection by indirectly promoting immediate antiviral response." (PMID 31311882, 2019). "The observed elevation of ISGs, encompassing ISG15, IFI6, IFIT1, IFIT2, IFIT3, IFI44L, and IFITM3, highlights SARS-CoV-2’s ability to activate the host’s interferon response—a critical defence mechanism against viral infection." (PMID 39940816, 2025). "IFN-stimulated genes (ISGs), including CRP, IFIT1, LRG1, SLC1A1, and CDKN1A, were upregulated during HBoV1 infection, suggesting that viral infection elicited an antiviral response from the host cell." (PMID 39846742, 2025). "IFN-induced protein with tetratricopeptide repeats 1 (IFIT1): The human IFIT family is comprised of 4 members (IFIT1, IFIT2, IFIT3 and IFIT5) and has been shown to play a role during viral infection." (PMID 38711929, 2024).
viral infection (continued). "In turn, IFNs induce the production of hundreds of ISGs, including ISG15, IFIT1, and RIGI itself, in a process that aims to control virus infection." (PMID 39403383, 2024). "And IFIT1, as one of the Interferon-stimulated genes (ISGs), was strongly induced by type I interferons (IFN-α and IFN-β), double-stranded RNA and viral infection." (PMID 38898490, 2024). "IFIT1 belong to one of the interferon stimulated genes (ISGs) family was obviously activated by type I interferon (IFN) and virus infection." (PMID 38321374, 2024). "Previous studies of viral infections have revealed the existence of IFNAR-independent pathways mediating the expression of ISGs, such as IFIT1, IFIT2, IFIT3 and ISG15, all of which were expressed by FVB/N macrophages during priming with M. ulcerans antigens." (PMID 37428812, 2023). "Interferon-induced protein with tetratrico-peptide repeats-1(IFIT1) and interferon-induced protein with tetratrico-peptide repeats-3 (IFIT3), both of which play an important role during viral infection, are upregulated in ΔMARCKS IMMs." (PMID 37790394, 2023). "WNV infection evades the anti-viral properties of interferon-induced protein with tetratricopeptide repeats 1 (IFIT1), an interferon-stimulated gene (ISG) protein that is highly activated after the viral infection." (PMID 37242305, 2023). "IFIT1, also induced by IFN stimulation and viral infection, plays an essential role in SLE immune disorders and tissue damage." (PMID 36655136, 2023). "These pathways are closely related to the ability to respond to viral infections, and many downstream genes of JAK/STAT1/2-ISGs signaling, including Oas2, Ifit1, and MX1, which have anti-viral activities." (PMID 36599833, 2023). "IFIT1 and OAS2 were closely related to the activation of the autoimmune system due to virus infection." (PMID 35831878, 2022). "It has been reported that interferon can significantly trigger the production of many interferon-induced genes (IFIT1, IFITM3, MX-1, OASL, ISG15, PKR, GBP1, Viperin, BST2, IRF-1, and CXCL10), which play key roles in the resistance to viral infection." (PMID 36337195, 2022). "We extended our analysis to a range of ISGs that have previously been identified as being regulated directly by virus infection in an IFN-independent manner i.e., IFIT1, IFIT2, IFIT3, ISG15, CXCL10, Mx1 and Mx2." (PMID 30871003, 2019). "Both ISG15 and IFIT1 are found to be induced rapidly and robustly after IFN stimulation upon viral infection." (PMID 28869524, 2017). "IFIT1, as well as ISG15, are interferon-induced genes reported to be activated immediately and robustly upon viral infection." (PMID 28869524, 2017). "IFIT1 is induced upon treatment with interferon (IFN), in particular IFN-α/β, and is better characterized in the context of a viral infection." (PMID 27161646, 2016). "The IFIT family includes four canonical human members (IFIT1, IFIT2, IFIT3, and IFIT5) and three mouse members (IFIT1, IFIT2, and IFIT3), which are induced upon simulation with IFN, virus infection, or other PAMP recognition." (PMID 24653722, 2014). "The antiviral-ISG, including GBP1, IFI44, IFIH1, IFIT1, MX1, and LY6E, were the most common group of up-regulated genes after influenza infection, yellow fever vaccination, and during febrile episodes of dengue hemorrhagic fever." (PMID 24069471, 2013). "Here we show that secretion of WNT2B and WNT9B and stabilization of β-catenin (CTNNB1) upon virus infection negatively regulate expression of representative inducible genes IFNB1, IFIT1 and TNF in a CTNNB1-dependent effector mechanism." (PMID 23785285, 2013). "Previously, it has been reported that in viral infections, m6A often positively correlates with gene expression in immune response pathways, as immune response genes are more active with higher m6A levels, like IFIH1, TNFAIP3, IFIT1 and IFIT2." (PMID 40989927, 2025).